RBMS1 (RNA binding motif single stranded interacting protein 1)
Diseases named in the same sentence as RBMS1 in open-access papers (continued):
Sharing a sentence is not in itself a finding about the gene and the disease.
prostate carcinoma (4 papers, 2020 to 2025). A carcinoma that arises from epithelial cells of the prostate gland. "Recent studies have identified RBMS1 as a tumor promoter that reduces susceptibility to breast, lung, gastric, colorectal, and prostate cancers in mice." (PMID 41214391, 2025). "In summary, we demonstrate the downregulation of RBMS1 in prostate cancer tissue which may be caused by increased miR-106b expression." (PMID 33093529, 2020). "A previous study has demonstrated that RBMS1 suppressed cell proliferation, albeit in prostate cancer." (PMID 37510319, 2023). "Overexpression of RBMS1 in prostate cancer cells resulted in diminished cell proliferation, colony forming ability as well as in retarded gap closing." (PMID 34804951, 2021). "We further identified RBMS1 as a new target gene for conversely deregulated miR-106b in prostate carcinoma." (PMID 33093529, 2020). "Our data indicate RBMS1 as a protein with tumour suppressive properties in PCa cell lines which is diminished in primary prostate carcinoma tissue." (PMID 33093529, 2020). "We show for the first time a deregulation of RBMS1 in connection with prostate cancer and demonstrate its decline in primary prostate tumours as well as in the PCa cell lines DU145 and LNCaP by qRT-PCR." (PMID 33093529, 2020). "Our results demonstrate for the first time a miR-106b dependent downregulation of RBMS1 in prostate carcinoma." (PMID 33093529, 2020). "Furthermore, we investigated RBMS1 function in DU145 and LNCaP prostate cancer cells after overexpression or reduction of RBMS1 and show inhibitory effects of RBMS1 on cell growth, gap closing and colony formation in PCa cell lines." (PMID 33093529, 2020). "Furthermore, we show for the first time tumour suppressive properties of RBMS1 in LNCaP and DU145 prostate cancer cells inhibiting cell growth, gap closing and colony forming ability and identify RBMS1 as a new player in prostate carcinoma." (PMID 33093529, 2020). "Overexpression of RBMS1 in DU145 and LNCaP prostate cancer cells resulted in diminished cell proliferation, colony forming ability as well as in retarded gap closing." (PMID 33093529, 2020).
cervical cancer (2 papers, 2021 to 2022). A primary or metastatic malignant neoplasm involving the cervix. "The result shows that POLR2J2, RBFOX3, RBMS1, ADARB1, AFF3, CSDC2 and CTIF were down-regulated in most of cervical cancer tissues compared with corresponding normal cervix tissues." (PMID 34863153, 2021).
diabetes (2 papers, 2016 to 2023). "Heterogeneity in effect size was observed at RBMS1 rs7593730 and GCC1-PAX4 rs6467136 (p < 10–4), whose associations with diabetes were significant only in Europeans and East Asians, respectively." (PMID 27053236, 2016).
glioma (2 papers, 2021 to 2026). A benign or malignant brain and spinal cord tumor that arises from glial cells (astrocytes, oligodendrocytes, ependymal cells). "The authors validated their findings using IHC on clinical samples, showing that RBMS1 overexpression is associated with a more aggressive glioma phenotype in patients." (PMID 41596318, 2026). "Researchers in China analyzed differentially expressed genes in gliomas and identified RBMS1 as a single potential predictor of immune infiltration levels." (PMID 41596318, 2026).
prostate tumors (2 papers, 2020 to 2022). "Reduced expression of RBMS1 was observed in prostate tumors and PCa cell lines, and RBMS1 showed inhibiting effect on PCa cell proliferation, suggesting RBMS1 acted as a tumor suppressor." (PMID 35611768, 2022). "Further analysis revealed a loss of RBMS1 expression in prostate tumours compared to corresponding normal tissue." (PMID 33093529, 2020). "CDKN2B-AS1, also known as ANRIL, is induced in prostate tumour tissue and could be another explanation for low RBMS1 abundance in PCa30." (PMID 33093529, 2020).
triple-negative breast carcinoma (2 papers, 2022). An invasive breast carcinoma which is negative for expression of estrogen receptor (ER), progesterone receptor (PR), and human epidermal growth factor receptor 2 (HER2). "The latest study report shows that B4GALT1 is a newly discovered PD-L1 glycosyltransferase, and in triple-negative breast cancer, RBMS1 can bind to the 3′-UTR of B4GALT1 to stabilize its mRNA." (PMID 36568388, 2022).
blood disease (1 paper, 2023). A disease that occurs in the blood. "RBMS1 is associated with DNA binding and is associated with the blood disease ‘blue toe syndrome’, while TANK is associated with signal transduction and the TRAF pathway and is associated with infectious neurological disorders (Nipah virus encephalitis)." (PMID 36672117, 2023).
breast tumors (1 paper, 2015). "Candidates that exhibited the strongest association with breast tumors were regions from the longest introns of RFX2, EPAS1, RBMS1, ZEB2, and the three different introns of CRIM1." (PMID 25798919, 2015).
cardiac hypertrophy (1 paper, 2025). "The focus of this study is to elucidate the mechanism by which RBMS1 participates in myocardial hypertrophy through CTTN splicing variant in cardiomyocytes." (PMID 41214391, 2025). "Additionally, significant increase in RBMS1 mRNA and protein were found in TAC mice, demonstrating that the significant increase of RBMS1 was associated with cardiac hypertrophy." (PMID 41214391, 2025). "In addition, we determined that the detrimental effects of RBMS1 overexpression in hypertrophy were eliminated by CTTN-Δe11 deficiency, demonstrating that the function of RBMS1 in cardiac hypertrophy depends on CTTN-Δe11." (PMID 41214391, 2025). "Furthermore, RBMS1 deficiency attenuated pathological cardiac hypertrophy both in vivo and in vitro." (PMID 41214391, 2025). "To elucidate the molecular mechanism by which RBMS1 promotes cardiac hypertrophy, we inspected the cellular localization of RBMS1." (PMID 41214391, 2025). "We found that overexpression of RBMS1 enhanced the expression of Ang II-induced cardiac hypertrophy markers β-MHC, ANP, and BNP in hiPSC-CMs (Fig. EV1A–C)." (PMID 41214391, 2025). "Although our investigation identified CTTN as a key functional mediator through which RBMS1 contributes to cardiac hypertrophy, we recognize that the study has certain limitations." (PMID 41214391, 2025). "To elucidate the potential role of RBMS1 in cardiac hypertrophy, we conducted a comprehensive analysis of RNA sequencing dataset (GSE135055)." (PMID 41214391, 2025). "Taken together, these findings indicate that the RBMS1/Δe11 axis contributes to pathological cardiac hypertrophy by facilitating the conversion of PIP2 to PIP3 through P100α, consequently leading to the activation of the PI3K-AKT signaling pathway." (PMID 41214391, 2025). "In the cardiac tissues of patients with DCM and in mice exhibiting myocardial hypertrophy, we observed elevated expression levels of RBMS1." (PMID 41214391, 2025). "Together, these results demonstrate that treatment with NTP is capable of alleviating cardiac hypertrophy and heart remodeling, and pharmacologically silencing RBMS1 provides proactive treatment strategies for the clinical treatment of cardiac hypertrophy." (PMID 41214391, 2025). "To further investigate the function of RBMS1 in cardiac hypertrophy, we explored the therapeutic effect of targeting RBMS1 on cardiac hypertrophy." (PMID 41214391, 2025). "To investigate the effects of RBMS1 on cardiac hypertrophy, we conducted a targeted overexpression study using adeno-associated virus 9 (AAV9) driven by the cardiomyocyte-specific troponin T2 (cTnT) promoter." (PMID 41214391, 2025). "Here, our results showed that cardiomyocyte-specific overexpression of RBMS1 via AAV9 injection aggravated cardiac hypertrophy induced by TAC." (PMID 41214391, 2025). "Taken together, these results demonstrate that the regulation of cardiac hypertrophy by RBMS1 is relied on the splicing of CTTN to generate CTTN-Δe11." (PMID 41214391, 2025). "Consistently, transmission electron microscopy and immunofluorescence demonstrated that RBMS1 exacerbated cardiac hypertrophy by disrupting the sarcomere and cytoskeleton of cardiomyocytes." (PMID 41214391, 2025). "Overexpression of RBMS1 aggravated transverse aortic constriction (TAC)-induced cardiac hypertrophy, whereas cardiac-specific RBMS1 deficiency attenuated cardiac hypertrophy and improved cardiac dysfunction in TAC-induced mice." (PMID 41214391, 2025). "Here, for the first time, we discovered elevated expression of RBMS1 in heart tissues of patients with dilated cardiomyopathy and in mice with cardiac hypertrophy." (PMID 41214391, 2025). "Our results imply that the upregulation of the PI3K/AKT pathway by RBMS1 and CTTN-Δe11 is a pathogenic factor in cardiac hypertrophy." (PMID 41214391, 2025). "Collectively, these findings manifest that cardiac-specific overexpression of RBMS1 exacerbates cardiac hypertrophy both in vivo and in vitro." (PMID 41214391, 2025).
cardiac hypertrophy (continued). "To clarify the conserved function of RBMS1 in regulating cardiac hypertrophy among species, we induced human induced pluripotent stem cell-derived cardiomyocytes (hiPSC-CMs) and constructed a plasmid that overexpressing human RBMS1." (PMID 41214391, 2025). "Furthermore, to elucidate the function of RBMS1 on cardiac hypertrophy in vitro, RBMS1 was silenced in NMCMs with small interfering RNA targeting RBMS1 (si-RBMS1)." (PMID 41214391, 2025). "However, the specific contribution of RBMS1 to the regulation of cardiac hypertrophy remains to be elucidated." (PMID 41214391, 2025). "Additionally, pharmacological inhibition of RBMS1 by nortriptyline alleviated cardiac hypertrophy and heart failure." (PMID 41214391, 2025). "Furthermore, genetic knockout of RBMS1 or pharmacological inhibition of RBMS1 using nortriptyline were shown to ameliorate pathological cardiac hypertrophy and heart failure." (PMID 41214391, 2025). "Our research findings indicate that genetic deletion or pharmacological inhibition of RBMS1 expression can alleviate cardiac hypertrophy, thereby confirming that RBMS1 is a promising therapeutic target for the treatment of cardiac hypertrophy and heart failure." (PMID 41214391, 2025). "Moreover, cardiac-specific overexpression of RBMS1 significantly aggravated TAC-induced cardiac hypertrophy, characterized by an increase heart size, heart weight/body weight ratio, and heart weight/tibia length ratio." (PMID 41214391, 2025). "Targeting RBMS1 could offer a novel strategy to ameliorate pathological cardiac remodeling and improve outcomes in patients with cardiac hypertrophy." (PMID 41214391, 2025). "Given the results of inhibiting RBMS1 expression in mice through genetic interventions, along with the function of RBMS1 in hiPSC-CMs, there is substantial evidence to suggest that RBMS1 holds significant potential as a therapeutic target for the management of cardiac hypertrophy and heart failure." (PMID 41214391, 2025). "To uncover the underlying pathway of RBMS1 in pathological cardiac hypertrophy, we utilized WGCNA approach to construct RBMS1 co-expression module based on RNA sequencing dataset (GSE135055), and identified 279 genes (MEyellow) co-expressed with RBMS1 were the strongest association with HF." (PMID 41214391, 2025). "Subsequently, we assessed whether RBMS1 is involved in cardiac hypertrophy by splicing of CTTN." (PMID 41214391, 2025). "Thus, we speculated RBMS1 activated PI3K/AKT pathway through generating CTTN-Δe11 to regulated cardiac hypertrophy." (PMID 41214391, 2025). "However, in addition to CTTN, there are likely other unidentified target genes of RBMS1 that may play roles in cardiac hypertrophy via distinct biological processes or pathways." (PMID 41214391, 2025). "Altogether, the results show that RBMS1 activates the PI3K/AKT pathway via splicing CTTN to promote sarcomere chaos and cardiac hypertrophy." (PMID 41214391, 2025). "In this study, we found a significant upregulation of RBMS1 in heart tissues from DCM patients and in mouse models of cardiac hypertrophy." (PMID 41214391, 2025). "The activated alternative splicing of CTTN regulated by RBMS1 promotes disorganization of the cardiomyocyte sarcomere via activation of the PI3K/AKT pathway, ultimately contributing to cardiac hypertrophy." (PMID 41214391, 2025). "We identified CTTN as a downstream target of RBMS1 and hypothesized that RBMS1 regulates the organization of the sarcomere and cytoskeleton in cardiomyocytes by splicing CTTN to produce the CTTN-Δe11 isoform in cardiac hypertrophy." (PMID 41214391, 2025).
chronic obstructive pulmonary disease (1 paper, 2022). A chronic and progressive lung disorder characterized by the loss of elasticity of the bronchial tree and the air sacs, destruction of the air sacs wall, thickening of the bronchial wall, and mucous accumulation in the bronchial tree. "Circ-RBMS1 was found to be highly expressed in chronic obstructive pulmonary disease (COPD) patients." (PMID 35645336, 2022).
colorectal cancer (1 paper, 2011). A primary or metastatic malignant neoplasm that affects the colon or rectum. "RBMS1 is a transcription factor that has been suggested as an important factor in inducing apoptosis in mice, and has been shown to have predictive power on colorectal cancer recurrence in human patient cohorts." (PMID 22011431, 2011).
diffuse gastric adenocarcinoma (1 paper, 2022). An adenocarcinoma arising from the stomach. "RBMS1 overexpression was significantly associated with diffuse gastric adenocarcinoma (P < 0.001)." (PMID 35361764, 2022).
gastric adenocarcinoma (1 paper, 2022). "According to the meta-analysis of two datasets, overexpression of RBMS1 was detected in most diffuse and mixed gastric adenocarcinoma tissues and associated with poor prognosis." (PMID 35361764, 2022).
heart failure (1 paper, 2025). Inability of the heart to pump blood at an adequate rate to meet tissue metabolic requirements. "In our earlier research, we demonstrated that RBMS1 in fibroblasts promotes cardiac fibrosis and heart failure by regulating LM07 alternative splicing, which subsequently activates the AP-1/TGF-β pathway." (PMID 41214391, 2025).
hypertrophic cardiomyopathy (1 paper, 2025). A condition in which the myocardium is hypertrophied without an obvious cause. "Furthermore, the expression of RBMS1 was markedly increased in the hearts of patient with hypertrophic cardiomyopathy (HCM) from snRNA sequencing dataset (SCP1303)." (PMID 41214391, 2025). "A summary volcano plot depicted a substantial number of differentially expressed genes in response to RBMS1 overexpression, and these genes were markedly enriched in pathways related to cytoskeleton, ECM, and hypertrophic cardiomyopathy." (PMID 41214391, 2025).
leukemia (1 paper, 2009). A malignant (clonal) hematologic disorder, involving hematopoietic stem cells and characterized by the presence of primitive or atypical myeloid or lymphoid cells in the bone marrow and the blood.
metastatic tumors (1 paper, 2024). "We revealed that RBMS1 expression level was higher in most metastatic tumors than that in the matched primary tumors." (PMID 38342601, 2024).
steatosis (1 paper, 2025). Increased lipid within the cytoplasm of cells. "The 10 most significantly downregulated genes in NAFLD included genes protecting against steatosis (MET) and fibrosis (GAS5), cancer suppression (RBMS1), and genes downregulated in HCC (FNDC3B)." (PMID 40489530, 2025).
tumor (34 papers, 2009 to 2025). "Altogether, loss of RBMS1 stimulates anti-tumor T cell immunity and inhibits tumor growth in an immune-dependent manner." (PMID 35538152, 2022). "Here, we explored a prognostic model for the estimation of tumor-associated mortality in GC patients and revealed the RNA-binding protein RBMS1 as a candidate promoter gene for GC metastasis by analyzing GOBO and Oncomine high-throughput sequencing datasets for 408 GC patients." (PMID 35361764, 2022). "To determine whether RBMS1 ablation-mediated PD-L1 downregulation enhances anti-tumor immunity in vivo, we inoculated 4T1 cells with depleted RBMS1 or control into nude mice (immune deficient)." (PMID 35538152, 2022). "In the present study, we revealed the important role of RBMS1 as a candidate promoter gene for GC metastasis via analysis of a high-throughput sequencing dataset and clinical specimens and explored a prognostic model for the estimation of tumor-associated mortality in GC patients." (PMID 35361764, 2022). "Additionally, we show new tumour suppressive properties of RBMS1 whose observed loss may further elucidate the development of PCa." (PMID 33093529, 2020). "Meanwhile, inhibition of RBMS1 induced ferroptosis and restored the sensitivity of tumor cells to anticancer drugs." (PMID 41214391, 2025). "Our finding that RBMS1 is upregulated in metastatic lung cancer and depletion of RBMS1 suppresses tumor metastasis identifies RBMS1 as an attractive anti‐metastatic target." (PMID 38342601, 2024). "Tumor samples with high expression of RBMS1 exhibited increased S100P levels and the level of S100P was positively correlated to that of RBMS1 in clinical samples (R = 0.5587, P < 0.0378)." (PMID 38342601, 2024). "Targeting RBMS1 with NTP, a small molecular chemical inhibitor of RBMS1, attenuates tumor metastasis in a mouse lung metastasis model." (PMID 38342601, 2024). "Consistently, in vivo studies using a mouse model revealed that RBMS1 plays a critical role in tumor metastasis." (PMID 38342601, 2024). "A series of functional experiments in vitro and in vivo confirmed that knockdown of RBMS1 inhibited cell metastasis in NSCLC, indicating that RBMS1 is involved in NSCLC metastasis as a tumor promoter." (PMID 38342601, 2024). "We found that the expression level of RBMS1 was closely related to tumour number, tumour size, and TNM stage." (PMID 36989117, 2023). "The RNA binding motif single stranded interacting protein 1 (RBMS1) has been reported to play a critical role in tumour progression." (PMID 36989117, 2023). "CircEXOC6B was observed to repress tumor metastasis via promotion of interaction with RBMS1 (RNA binding motif single strand interacting protein 1) and HuR (human antigen R) in prostate cancer." (PMID 38152652, 2023). "More importantly, we identified the function of RBMS1 in potentiating ferroptosis and inhibiting tumour growth of HCC, which was regulated by circIDE/miR-19b-3p axis." (PMID 36989117, 2023). "Consistently, a recent publication also reported that RBMS1 is a critical regulator in PD-L1 expression and tumor immunity." (PMID 37628671, 2023). "As expected, re-expression of B4GALT1 promoted RBMS1-depleted 4T1 tumor growth in the immune competent model." (PMID 35538152, 2022). "Strikingly, the application of RBMS1-depletion with CTLA4 blockade demonstrated a significant improvement in tumor burden and survival rate of mice." (PMID 35538152, 2022). "Consistent with our mechanistic findings, flow cytometry analysis of mice tumor tissues revealed that depleted RBMS1 elevated CTL activities." (PMID 35538152, 2022). "It was shown that obvious accumulation of FDG was observed in RBMS1-OE mice relative to NC mice and the inhibition of tumor growth was significantly correlated with SUVmax." (PMID 35361764, 2022).